HARBI1 (harbinger transposase derived 1)
Description:
Transposase-derived protein that may have nuclease activity (Potential). Does not have transposase activity.
Synonyms: C11orf77; FLJ32675
Tractability: Antibody: its Gene Ontology location is reachable by antibodies, with high confidence; the Human Protein Atlas places it where antibodies can reach.
Gene: Protein-coding gene on chromosome 11 (46,601,439 to 46,617,909, reverse strand). Ensembl gene ENSG00000180423.
Subcellular location: Nucleus; Cytoplasm
Subcellular location (Human Protein Atlas): Cytosol; Plasma membrane
Gene Ontology:
Molecular function: protein binding
Cellular component: cytosol; plasma membrane; cytoplasm; nucleus
Genetic constraint (gnomAD): Loss-of-function variants: 15 observed, 26.5 expected, observed/expected ratio (o/e) 0.57, 90% interval 0.38 to 0.87. The upper end of that interval is the gene's LOEUF score, 0.87, which puts it in group 3 of 6, group 1 being the genes least tolerant of losing a copy. Missense variants: 396 observed, 470.4 expected, observed/expected ratio (o/e) 0.84, 90% interval 0.77 to 0.92. Synonymous variants: 168 observed, 169.14 expected, observed/expected ratio (o/e) 0.99, 90% interval 0.88 to 1.13.
Homologues: Orthologues: chimpanzee HARBI1 (99% identical), macaque HARBI1 (99% identical), dog HARBI1 (97% identical), pig HARBI1 (97% identical), rabbit HARBI1 (94% identical), rat Harbi1 (93% identical), guinea pig HARBI1 (92% identical), mouse Harbi1 (90% identical), tropical clawed frog harbi1 (72% identical), zebrafish harbi1 (62% identical), Drosophila melanogaster CG43088 (19% identical).